GOLGA2P10 (GOLGA2 pseudogene 10)
Synonyms: FLJ22795; AgSK1
Gene: Transcribed unprocessed pseudogene on chromosome 15 (82,476,498 to 82,477,926, reverse strand). Ensembl gene ENSG00000255769.
Diseases named in the same sentence as GOLGA2P10 in open-access papers:
GOLGA2P10 is named in the same sentence as 3 diseases in open-access papers, as found by Europe PMC text mining. Sharing a sentence is not in itself a finding about the gene and the disease. The quoted sentences say what the papers report.
hepatocellular carcinoma (2 papers, 2020 to 2022). A malignant tumor that arises from hepatocytes. "It was shown that golgin A2 pseudogene 10 (GOLGA2P10) lncRNA protects hepatocellular carcinoma cancer (HCC) cells from ER-stress-induced apoptosis by modulating the intrinsic pathway." (PMID 37533667, 2022). "Here, we found that a pseudogene-derived lncRNA, Golgin A2 pseudogene 10 (GOLGA2P10), was frequently upregulated in HCC tissues and significantly elevated in hepatoma cells treated with ER stress inducers, such as tunicamycin and thapsigargin." (PMID 32332695, 2020).
cancer (1 paper, 2020). A tumor composed of atypical neoplastic, often pleomorphic cells that invade other tissues. "In this study, we identify a new lncRNA GOLGA2P10 and reveal that it is induced by ER stress and prevents cancer cells from ER stress-induced apoptosis by upregulating BCL-xL and increasing BAD phosphorylation, indicating GOLGA2P10 as a potential target for cancer therapy." (PMID 32332695, 2020).
tumor (1 paper, 2020). "Taken together, ER stress may upregulate GOLGA2P10 through the PERK/ATF4/CHOP pathway, and the elevated GOLGA2P10 may confer tumor cells with resistance to ER stress-induced apoptosis by increasing the protein level of BCL-xL and the phosphorylation of BAD." (PMID 32332695, 2020).